AVP (arginine vasopressin)
Diseases named in the same sentence as AVP in open-access papers (continued):
Sharing a sentence is not in itself a finding about the gene and the disease.
Obesity (continued). "Although the precise mechanism that increases OXT and AVP expression by CRTC deficiency remains unknown, the increase in OXT and AVP expression may be a homeostatic adaptation to HFD or obesity." (PMID 35020776, 2022). "Moreover, our present data are supported by previous data linking disturbances of the AVP system to measures of obesity and DM." (PMID 26503846, 2016). "AVP may demonstrate important metabolic effects that impact obesity pathophysiology." (PMID 40428796, 2025). "However, in most studies, copeptin was independently associated with insulin resistance, obesity, and T2DM in adjusted models, which evidences its contribution, as an indirect marker of the AVP regulatory system in metabolic disorders and key components of MetS in different populations." (PMID 36317191, 2022). "Therefore, a decreased mRNA level of V2R may, to a certain extent, attenuate AVP-mediated water and sodium reabsorption in the kidneys, and therefore avoid water retention in obesity, especially during low renal filtration." (PMID 32929357, 2020).
syndrome of inappropriate antidiuretic hormone secretion (31 papers, 2012 to 2026). "Syndrome of inappropriate antidiuretic hormone secretion can be caused by arginine-vasopressin-producing tumors or enhanced arginine vasopressin secretion from the posterior pituitary gland due to central nervous system disorders and intrathoracic diseases." (PMID 34289912, 2021). "Copeptin is a stable surrogate biomarker of arginine vasopressin (AVP), directly linked to ADH secretion, and has proven diagnostic accuracy in water balance disorders, including syndrome of inappropriate antidiuretic hormone secretion (SIADH)." (PMID 40430232, 2025). "The syndrome of inappropriate antidiuretic hormone secretion (SIADH) is characterized by the excessive retention of free water due to unregulated release of antidiuretic hormone (ADH, or arginine vasopressin)." (PMID 41589165, 2025). "Large clinical samples must be examined to verify the differential proteins identified in this study before these proteins are used as biomarkers for pathological AVP increased diseases, such as syndrome of inappropriate antidiuretic hormone secretion (SIADH)." (PMID 28560103, 2017).
COVID-19 (28 papers, 2020 to 2025). A disease caused by infection with severe acute respiratory syndrome coronavirus 2. "The inflammation, pain, lung injury, plasma osmolarity changes and psychological stress associated with COVID-19 are behind the activation of the stress-adapting endocrine axis with a consequent increase in circulating AVP/copeptin." (PMID 35350852, 2022). "SARS-CoV-2 might play a role in the pathogenesis of Menière's through the elevation of plasma arginine vasopressin (pAVP) caused by stress due to COVID-19 and forced quarantine and by inducing an inflammatory state that could lead to the production of autoantibodies against the endolymphatic sac." (PMID 35098491, 2022). "Various in silico studies confirmed the potential of AVP analogues in COVID-19 treatment." (PMID 35328489, 2022). "Furthermore, it was shown that body functions regulated by AVP (regulation of the blood osmotic system, blood pressure, plasma volume and body water content) are disrupted during COVID-19 and related with poor clinical outcomes." (PMID 35328489, 2022). "During admission when the patients presented with low levels of sodium and suspected SIADH, the potential high release of AVP could be a part of the procoagulant state of COVID-19 further impaired by hyperosmolality which also increases the risk of venous thromboembolism." (PMID 34156969, 2021). "Increased release of AVP into the circulation and elevated levels of its surrogate marker copeptin are found in pulmonary diseases, arterial hypertension, heart failure, obstructive sleep apnoea, severe infections, COVID-19 due to SARS-CoV-2 infection, and brain injuries." (PMID 34867449, 2021). "In addition, patients with pain, nausea or pneumonia related to COVID-19 can develop SIADH through the non-osmotic release of arginine vasopressin induced by increased levels of cytokines and inflammation." (PMID 37744432, 2023).
Hypoglycemia (25 papers, 2009 to 2025). A decreased concentration of glucose in the blood. "Insulin-induced hypoglycemia causes AVP release into the circulation both in animals and in human subjects." (PMID 34867449, 2021). "Insulin induced similar hypoglycemia in fasting normal and AVP-deficient mothers with smaller ACTH reaction in AVP-deficient dams (first columns)." (PMID 24550698, 2014). "It is likely that AVP plays an essential role in the regulation of ACTH secretion during hypoglycemia and stress, because AVP-deficient Brattleboro rats manifest reduced elevations of plasma ACTH and corticosterone levels during hypoglycemia and exposure to various types of stressors." (PMID 38279313, 2024). "Potent stimuli to AVP release are increasing plasma osmolality and unspecific stimuli, such as nausea, pain, or hypoglycemia." (PMID 39863827, 2025). "It has been also shown that the increased release of AVP during hypoglycemia significantly contributes to the stimulation of ACTH secretion." (PMID 38279313, 2024). "There is evidence that AVP participates in the regulation of glycemic responses during hypoglycemia." (PMID 38279313, 2024). "Studies on mice revealed the presence of V1bR mRNA at the pancreatic α-cells and showed that enhanced release of AVP and stimulation of V1bR play a significant role in the elevation of glucagon release during insulin-mediated hypoglycemia." (PMID 39769071, 2024). "AVP also mediates the stimulatory effects of hypoglycemia produced by exogenous insulin and 2-deoxy-D-glucose on glucagon secretion." (PMID 34787082, 2021). "Similar to insulin-induced hypoglycemia, 2-DG administration leads to elevated AVP levels in both humans and experimental animals." (PMID 34752420, 2021). "We show that the A1/C1 neurons of the medulla oblongata drive AVP neuron activation in response to insulin-induced hypoglycemia." (PMID 34787082, 2021). "Insulin-induced hypoglycemia enhances population activity of AVP neurons in the supraoptic nucleus (SON), driving glucagon secretion AAV-DIO-hM3Dq-mCherry was injected bilaterally into the SON of Avpires-Cre/+ mice." (PMID 34787082, 2021). "Preclinical and clinical studies have shown that insulin-induced hypoglycemia leads to increased plasma AVP levels." (PMID 34752420, 2021). "The main stimuli that trigger AVP release include hyperosmolality, hypovolemia, hypotension, hypoxia, hypoglycemia, strenuous exercise, and angiotensin II (Ang II) and the same stimuli are known to affect pulmonary ventilation." (PMID 34867449, 2021). "We found that plasma AVP levels during hypoglycemia vary between 1 pM and 30 pM, in good agreement with previous studies measuring AVP with a radioimmunoassay in human and rat." (PMID 34787082, 2021). "SSR149415 treatment abolished insulin-induced glucagon secretion, showing that intact AVP/V1bR signaling is required for efficient glucagon release following insulin-induced hypoglycemia." (PMID 34752420, 2021). "The widely accepted view is that the activation of A1/C1 neurons (and consequently AVP neurons) during hypoglycemia depends on peripheral glucose sensing at multiple sites, including the hepatic portal system." (PMID 34787082, 2021). "Given the relatively small increase in circulating copeptin in response to hypoglycemia, we used pharmacological and genetic approaches to more conclusively establish the link between AVP and counter-regulatory glucagon during hypoglycemia." (PMID 34787082, 2021). "We also demonstrate that AVP neuron activity is elevated during hypoglycemia induced by either 2DG or exogenous insulin." (PMID 34787082, 2021). "The importance of AVP along with CRH as physiological modulators of ACTH secretion in response to insulin-induced hypoglycemia has been demonstrated in humans." (PMID 23486926, 2013). "AVP also plays an important role in regulating glucagon secretion during hypoglycemia." (PMID 40428796, 2025).
Hypoglycemia (continued). "The ICV infusion of insulin in doses that do not cause systemic hypoglycemia increased the secretion of AVP in a dose-dependent manner." (PMID 38279313, 2024). "In addition, hypoxia and hypoglycemia are able to stimulate AVP release, whereas vasopressin elevates blood glucose levels and increases brain glucose retention." (PMID 38279313, 2024). "Moreover, it has been shown that hypoglycemia stimulates the release of AVP and that the glucosensitive receptors engaged in the regulation of AVP release are located inside the blood–brain barrier." (PMID 38279313, 2024). "Frequently, hypoglycemia and stress stimulate the release of AVP together with CRH." (PMID 38279313, 2024). "As discussed in other studies, synthesis and release of AVP are regulated by body fluid osmolality, signals from cardiovascular receptors and chemoreceptors, tissue hypoxia, oxidative stress, hypoglycemia, and several types of stressors engaging rich sets of neurotransmitters and hormones." (PMID 39769071, 2024). "We investigated the role of AVP in regulating glucagon secretion in vivo during hypoglycemia." (PMID 34787082, 2021). "The hypoglycemia-induced AVP release counteracts low plasma concentrations of glucose by gluconeogenic and glycogenolytic effects of AVP in the liver and on the AVP-induced activation of the hypothalamic-pituitary-adrenal cortex axis resulting in glucocorticoid release." (PMID 34867449, 2021). "We first explored the role of AVP during hypoglycemia, a potent stimulus of glucagon secretion." (PMID 34787082, 2021). "We therefore hypothesized that hypoglycemia-induced AVP release is due to projections from A1/C1 neurons." (PMID 34787082, 2021). "Several studies have demonstrated increases in AVP after induction of hypoglycemia." (PMID 30678725, 2019). "AVP deficient Brattleboro rats have a blunted corticosterone response to some but not all stressors, while elegant studies using immuno-neutralization of AVP also reported a blunted HPA response to a range of stressors including restraint, insulin-induced hypoglycemia and lipopolysaccharide." (PMID 33905792, 2021). "We hypothesize that under conditions of hypoxia, oligo/hypovolemia, hypotonia, hypoglycemia, exercise, activation of renin-angiotensin system, the increase in AVP plasma concentration may help in limiting excessive increase in ventilation and prevent development of hypocapnia." (PMID 34867449, 2021). "Therefore, a VHN-BNST circuit may also be important for driving AVP neuron activity in response to hypoglycemia, explaining why A1/C1 inhibition only partially prevented the activation of AVP neurons." (PMID 34787082, 2021). "Studies, where pituitary portal blood was sampled, have been able to show that AVP is released preferentially over CRH in some cases, including insulin-induced hypoglycemia." (PMID 33905792, 2021). "We have previously demonstrated the prominence of AVP/Avpr1b in the plasma ACTH and CORT responses to acute insulin-induced hypoglycaemia stress in mice." (PMID 20846299, 2010). "Second, hypoglycaemia is one of the most potent non-osmotic stimuli for the pituitary gland and induces an AVP release." (PMID 39863827, 2025). "It has been reported that insulin-induced hypoglycemia increases the secretion of cortisol, but it does not affect plasma AVP levels." (PMID 39000501, 2024). "It has been proven that hypoglycaemia, being a nonosmotic stimulus, leads to a three-fold increase in AVP concentration." (PMID 36359377, 2022). "Insulin-induced hypoglycemia is considered to act on the hypothalamus, where it strongly stimulates ACTH secretion by inducing the release of both corticotropin-releasing hormone (CRH) and arginine vasopressin (AVP)." (PMID 36494805, 2022). "Our results did, however, demonstrate a significant and strong relationship between [AVP]p and blood glucose levels, supporting the possible contribution of hypoglycemia to the non-osmotic stimulation of AVP." (PMID 30678725, 2019).
Hypoglycemia (continued). "Any ACTH and corticosterone response to hypoglycemia in the neonatal period appears to be mediated by arginine vasopressin (AVP) and not CRH." (PMID 26343738, 2015). "Thus, the study using V1b receptor knockout mice demonstrated the importance of AVP and V1b receptor for a normal response of the HPA axis to heterotypic stressor (hypoglycemia) in chronic stress induced by repeated restraint." (PMID 23486926, 2013). "The increased release of AVP in response to hypoglycemia appears to be independent of insulin." (PMID 34867449, 2021).
hypothyroidism (25 papers, 2012 to 2025). Abnormally low levels of thyroid hormone. "This is due to elevated AVP levels, mainly attributed to the hypothyroidism-induced decrease in cardiac output." (PMID 39240512, 2024). "Although copeptin is a more reliable humoral marker of ADH/AVP production, its alterations have not been investigated in hypothyroidism." (PMID 36187132, 2022).
chronic kidney disease (24 papers, 2010 to 2025). Impairment of the renal function secondary to chronic kidney damage persisting for three or more months. "Urine flow affects the formation of kidney stones and recurrence of urinary tract infection, while increased circulating AVP is implicated in metabolic disease, chronic kidney disease, and autosomal dominant polycystic kidney disease." (PMID 32632658, 2021). "Previous studies have shown that AVP is associated with the progression of chronic kidney disease." (PMID 33471240, 2021). "AVP may also play a significant role in salt-sensitive hypertension in chronic kidney disease (CKD) patients due to a higher level of AVP causing activation of preglomerular V1a receptors and V2 receptors in collecting tubule." (PMID 25853137, 2015). "Chronic kidney disease patients are at high risk for cardiovascular events, often suffer from disturbances of sodium homeostasis and may have an overly activated AVP system." (PMID 24215469, 2013). "Heightened AVP levels may aggravate chronic kidney disease, while high serum osmolality may induce renal tubular injury and fibrosis via the sympathetic nervous system and aldose reductase pathway, culminating in oxidative stress." (PMID 39076508, 2024). "Experiments in rats and human observational studies suggest that AVP may play a role in the genesis and exacerbation of renal damage and chronic renal insufficiency." (PMID 34926704, 2021). "Interestingly, recent work using the synthetic analogue of AVP, desmopressin, has also suggested a potential role for AVP in inducing chronic kidney disease following recurrent heat stress in mice." (PMID 29075863, 2018). "Acting upon V2 receptors expressed in the kidney, AVP appears to contribute to the progression of chronic kidney disease and decline in glomerular filtration rate and may be involved in the progression of autosomal dominant polycystic kidney disease (ADPKD)." (PMID 25866433, 2015). "AVP may also play a role in the progression of chronic kidney disease and effect physiologic changes relating to aging, abnormal social behavior, and cognitive function." (PMID 25853137, 2015). "Similarly, AVP-dependent changes were found in elderly people, patients with congenital heart failure, or chronic kidney disease." (PMID 24375010, 2014). "Among several variables, the multiple regression analysis demonstrated that e-GFR was the most important factor to determine the extent of disturbance in the AVP-AMP-AQP2-axis, and thus the degree of deterioration in urine concentrating and diluting ability in chronic kidney disease." (PMID 20923561, 2010). "Elevated AVP may also affect albuminuria via vasopressin receptor 2 activation and worsen peripheral insulin resistance in nondiabetic chronic kidney disease patients." (PMID 40317183, 2025).
Hyperglycemia (24 papers, 2010 to 2026). An increased concentration of glucose in the blood. "Elevated AVP levels have been associated with enhanced hepatic gluconeogenesis and glycogenolysis, contributing to hyperglycemia and the development of insulin resistance—both key drivers of hepatic lipid accumulation." (PMID 40428796, 2025). "Recently, experiments on Sprague Dawley rats and lean Zucker rats confirmed that acute AVP administration causes hyperglycemia, mediated by V1aR receptors, and that this is followed by secretion of insulin and a decrease in blood glucose level." (PMID 39769071, 2024). "Alpha-2- agonists are known to increase urine production in awake and anaesthetized healthy equids, mainly due to a reduced secretion rate of arginine vasopressin and due to hyperglycemia caused by hypoinsulinemia." (PMID 35818051, 2022). "A significant relationship was found between high copeptin levels and reduced insulin sensitivity, as well as between AVP gene tagSNPs (CC genotype rs6084264, TT genotype rs2282018, C allele rs2770381, and CC genotype rs1410713) and the incidence of hyperglycemia." (PMID 39000501, 2024). "For example, significant associations were observed between the tagSNPs of the AVP gene (CC genotype of rs6084264, the TT genotype of rs2282018, the C-allele of rs2770381, and the CC genotype of rs1410713) and the incidence of hyperglycemia and decreased insulin sensitivity." (PMID 33905792, 2021). "Thus, AVP has a role in causing hyperglycemia by not only acting on islet cells but through its action on V1b receptors in the pituitary." (PMID 25853137, 2015). "Secretion of AVP and activation of AVP receptors are regulated by changes in blood pressure and body fluid osmolality, hypoxia, hyperglycemia, oxidative stress, inflammation, and several metabolic hormones; moreover, AVP turnover is regulated by insulin." (PMID 39769071, 2024). "Hyperglycemia induced by chronic AVP infusion was diminished by concomitant treatment with V1a receptor antagonist, whereas, insulin levels were the same as the group that had normal AVP concentration." (PMID 33905792, 2021). "If the urine osmolality is above this value, then other etiologies that are not primarily caused by impaired AVP secretion or action have to be ruled out, such as hyperglycaemia or hypercalcaemia." (PMID 33916272, 2021). "The AVP-induced hyperglycaemia may have also created an osmotic stimulus further stimulating AVP secretion." (PMID 31141915, 2019). "Thus, AVP might have a role in the induction of hyperglycemia during critical illness." (PMID 33882083, 2021). "Chronically high AVP levels induce hyperglycemia in healthy nonobese rats as well as aggravate glucose tolerance and insulin resistance in obese rat models, while treatment with V1aR antagonist reverses these changes." (PMID 40428796, 2025). "Although the study was unable to determine the temporal direction of the hyperglycaemia-AVP relationship, considering the elevated AVP was accounted for by hypovolemia, it is likely that the hyperglycaemia drove higher AVP, rather than vice versa." (PMID 31141915, 2019).
Adrenal insufficiency (23 papers, 2011 to 2025). Insufficient production of steroid hormones (primarily cortisol) by the adrenal glands. "Hypotension in adrenal insufficiency is caused by increases in arginine vasopressin, reduced aldosterone and sodium wasting." (PMID 32307006, 2020). "Moreover, akin to adrenal insufficiency, removal of the adrenal glands causes marked increases in plasma AVP levels." (PMID 22934055, 2012). "This muddies the waters with respect to whether AVP-dependent stimulation of ENaC in adrenal insufficiency is a compensatory response to decreases in volume or a result independent of actions on vascular volume." (PMID 22934055, 2012).